MIR1244-1 (microRNA 1244-1)
Synonyms: hsa-mir-1244; MIR1244; MIRN1244; hsa-mir-1244-1
Gene: MicroRNA gene on chromosome 2 (231,713,314 to 231,713,398, forward strand). Ensembl gene ENSG00000284378.
Homologues: Paralogues in human: MIR1244-2 (100% identical), MIR1244-3 (100% identical), MIR1244-4 (100% identical).